MALAT1 (metastasis associated lung adenocarcinoma transcript 1)
Diseases named in the same sentence as MALAT1 in open-access papers (continued):
Sharing a sentence is not in itself a finding about the gene and the disease.
lung adenocarcinoma (continued). "In 75 tumors with advanced lung adenocarcinoma, higher expression levels of MALAT1 were seen in tissues from M1 or Mx patients than those from M0 patients (P = 0.049)." (PMID 28253859, 2017). "A previous study showed that MALAT1 was able to promote lung adenocarcinoma cell epithelial–mesenchymal transition (EMT) and metastasis by downregulation of expression of the targeting gene, SLUG, as a ceRNA for miR-204." (PMID 28977880, 2017). "Another study in lung adenocarcinoma demonstrated that lncRNA MALAT1 exerted oncogenic functions by targeting miR-204." (PMID 28396617, 2017). "MALAT-1 lncRNA was first identified in a cDNA subtractive hybridization experiment from metastasizing lung adenocarcinoma in 2000." (PMID 26935426, 2016). "We found that MALAT1, a lncRNA gene previously shown to be involved in tumorigenesis of lung adenocarcinomas, exhibits a slightly significant FM bias in cohorts of both the WG-505 (p value 0.0138 in KIRC) and the WG-608 (p value 0.0104 in pan-cancer) datasets." (PMID 27311963, 2016). "For example, lncRNA HOTAIR increases cisplatin resistance in human lung adenocarcinoma cells, lncRNA MALAT-1 increases chemo-resistance to anticancer drugs in pancreatic cancer." (PMID 27270310, 2016). "Reportedly, the lncRNAs class MALAT-1 has been found to promote cell motility in lung adenocarcinoma cells." (PMID 25167886, 2014). "The present results demonstrate the significance of MALAT-1 for the prediction of the metastasis and prognosis of lung adenocarcinoma." (PMID 24137407, 2013). "Short-interfering RNA-mediated MALAT-1 silencing has been shown to impair the in vitro cell motility of lung adenocarcinoma cells." (PMID 24137407, 2013). "MALAT1 was first discovered during carcinogenesis in lung adenocarcinoma, hence its name." (PMID 38674413, 2024). "Cell cycle results showed that overexpression of MALAT-1 could increase the proliferation activity of lung adenocarcinoma cells, while knockout of MALAT-1 could effectively reduce the proliferation activity of cells." (PMID 39196297, 2024). "Indeed, in unpublished work from our lab, CRISPR activation-guided epigenetic overexpression of endogenous Malat1 in an autochthonous mouse model of lung adenocarcinoma confirmed that increased Malat1 expression is a driver of cancer progression." (PMID 39195572, 2024). "Knockout of MALAT-1 can increase the apoptosis rate of lung adenocarcinoma cells." (PMID 39196297, 2024). "Moreover, MALAT1 is found to work as a prognosis marker in lung adenocarcinoma and squamous cell lung carcinoma." (PMID 36934373, 2023). "MALAT1 was known as a metastasis development marker for lung adenocarcinoma in the early stages." (PMID 35281907, 2022). "MALAT1 was initially reported as a biomarker of metastasis in the early lung adenocarcinoma." (PMID 36685103, 2022). "MALAT1 also inhibits miR-200b function in DTX (docetaxel)-resistant lung adenocarcinoma cells." (PMID 34976181, 2022). "MALAT1 acts as a ceRNA for miR-429 to regulate RHOA expression in lung adenocarcinoma cells." (PMID 34771549, 2021). "MALAT-1 enhanced cell motility of lung adenocarcinoma by downregulating CCT4." (PMID 33815471, 2021). "For instance, MALAT1 could upregulate the expression of miR-204-5p target gene SLUG through competitively ‘sponging’ miR-204-5p to form a branch of the MALAT1/miR-204/SLUG pathway to regulate the progression of lung adenocarcinoma." (PMID 29285225, 2017).
lung adenocarcinoma (continued). "Therefore, it would be of interest to explore and concomitantly correlate miR-9, SRSF1 and MALAT-1 expression in lung adenocarcinoma metastatic cells and in primary tumors, and also to correlate their levels with EMT markers and lamin A expression." (PMID 28806747, 2017). "We further tested the TCGA data, and found that a higher expression of MALAT1 was associated with metastatic of advanced lung adenocarcinoma but not with lung squamous cell carcinoma." (PMID 28253859, 2017). "MALAT-1 (metastasis associated lung adenocarcinoma transcript-1, also called NEAT2) is a predictive marker for metastasis and shorter survival in early stage lung adenocarcinoma." (PMID 28672805, 2017). "MALAT-1 (metastasis-associated lung adenocarcinoma transcript 1 also called NEAT2 or nuclear enriched abundant transcript 2) was first identified in NSCLC as a predictive marker associated with metastatic disease and shorter survival in early stage lung adenocarcinoma." (PMID 29701689, 2018). "LncRNA MALAT1, also known as NEAT2 (noncoding nuclear-enriched abundant transcript 2), was initially demonstrated to be positively associated with metastasis and shorter survival in non-small cell carcinoma (NSCLC) patients, specifically in the early stages of lung adenocarcinoma." (PMID 30116729, 2018). "In conclusion, this study revealed that the genetic variation SNP rs3200401 T allele located on lncRNA MALAT1 was associated with a better survival of advanced lung adenocarcinoma patient, while this effect was not seen among lung squamous cell carcinoma patients." (PMID 28253859, 2017). "MALAT1 rs3200401 genotype distribution and clinicopathologic characteristics of EGFR wild type lung adenocarcinoma patients." (PMID 38517388, 2024). "In respiratory system tumors, MALAT1 was originally identified as a prognostic marker for metastasis and patient survival in NSCLC, specifically in early stages of lung adenocarcinoma." (PMID 26055877, 2015). "The present study identified that the expression of MALAT-1 was significantly higher in the stage II and IIIA samples than in stage I lung adenocarcinoma, which was consistent with the published data." (PMID 24137407, 2013). "Compared with the stage I samples, NAG-1, MAGE-A3, MALAT-1 and MMP-12 were significantly upregulated in stage II and IIIA lung adenocarcinoma samples." (PMID 24137407, 2013). "In cytoplasm, MALAT1 weakens the binding of miR-200b to E2F transcription factor 3(E2F3) and ZEB1 mRNAs, thus leading to increase of E2F3 and ZEB1 protein expression and chemoresistance of lung adenocarcinoma cells." (PMID 34976181, 2022). "Besides, Chen and colleagues found that TFAP2C could activate the expression of MALAT1 and thus modulate the chemoresistance of DTX-resistant lung adenocarcinoma cells." (PMID 35402284, 2022). "More importantly, it has been confirmed that lncRNA MALAT1 can release EZH2 by binding to PRC2 complex, of which EZH2 is a main component thus blocking transcriptional inhibition of downstream genes and consequently promoting the expression of HIV-1 in lung adenocarcinoma." (PMID 33292221, 2020).
ovarian carcinoma (90 papers, 2010 to 2025). A malignant neoplasm originating from the surface ovarian epithelium. "Further, several lncRNAs have been linked with p-53 in ovarian cancer, of which H19, MALAT1, PVT1 and LINC-ROR are upregulated while MEG3 and PANDA are known to be downregulated." (PMID 39912983, 2025). "MALAT1 knockdown in ovarian cancer cells resulted in upregulation of miR-218 with loss of proliferation and cell cycle arrest." (PMID 39912983, 2025). "In this regard, MALAT-1 is a cancer-causing gene in ovarian cancer, and its blockade significantly hinders EMT." (PMID 38511067, 2024). "In ovarian cancer, MALAT1 is often upregulated and has been associated with lower individual survival rates, indicating reduced life expectancy and increased risk of disease progression." (PMID 39323624, 2024). "Metastasis-associated lung adenocarcinoma transcript 1 (MALAT1) is one of the earliest cancer-related lncRNAs identified to be related to ovarian cancer." (PMID 35103065, 2022). "The expression level of MALAT1 is associated with ovarian cancer cells with different metastatic potentials." (PMID 35103065, 2022). "Fusions of MALAT1, a lncRNA associated with poor survival in metastasis in several tumor types, were recently observed at high frequency (13/18, 72%) in ovarian cancer and TNBC patients after PARPi treatment." (PMID 36344544, 2022). "A similar study confirms the upregulation of MALAT1 in ovarian cancer cell lines, and tumor tissues which was associated with poor prognosis." (PMID 34204094, 2021). "For example, metastasis associated lung adenocarcinoma transcript 1 (MALAT1) is an lncRNA which is upregulated in ovarian cancer and associated with poor prognosis in ovarian cancer patients." (PMID 34681900, 2021). "LncRNA metastasis-associated lung adenocarcinoma transcript 1 (MALAT1) has been reported to be upregulated and to contribute to ovarian cancer tumorigenesis." (PMID 34512721, 2021). "In human ovarian cancer tissues, high MALAT1 expression is associated with advanced disease stage, recurrence, and reduced survival." (PMID 32174966, 2020). "TDEs containing MALAT1 (metastasis-associated lung adenocarcinoma transcript 1) which is associated with angiogenesis and metastasis in epithelial ovarian cancer (EOC), induce pro-angiogenesis gene expression in human umbilical vein endothelial cells (HUVECs)." (PMID 30940145, 2019). "Both of these two studies focused on exploring association between lncRNA UCA1 or MALAT-1 and OS in all human cancers, ovarian cancer is just one of them." (PMID 28118613, 2017). "We found that MALAT-1 mRNA was overexpressed in tumor tissuesand MALAT-1 expression was associated with ovarian cancer progression." (PMID 27227769, 2016). "Our current study demonstrates that upregulation of MALAT-1 is associated with ovarian cancer progression." (PMID 27227769, 2016). "Association of MALAT-1 expression with clinicopathological charateristics of ovarian cancer patients." (PMID 27227769, 2016). "We found that upregulation of MALAT-1 mRNA in ovarian cancer tissues and enhanced MALAT-1 expression was associated with FIGO stage." (PMID 27227769, 2016). "Similarly, elevated serum exosomal metastasis-associated lung adenocarcinoma transcript 1 (MALAT1) promoted angiogenesis and was highly correlated with an advanced and metastatic phenotype of epithelial ovarian cancer." (PMID 38392967, 2024). "Similarly, metastasis-associated lung adenocarcinoma transcript 1 (MALAT1) was identified to be highly expressed in ovarian cancer cells, thereby promoting EMT, anchorage independence growth, and metastasis." (PMID 33854965, 2021). "In addition, MALAT1 decreased sensitivity of cisplatin in ovarian cancer was also reported to be associated with the Notch1 signaling pathway." (PMID 32708561, 2020). "Two novel mechanisms underlying MALAT1 involved in ovarian cancer were identified." (PMID 29921308, 2018).
ovarian carcinoma (continued). "Epithelial ovarian cancer cells derived exosomes could transfer metastasis-associated lung adenocarcinoma transcript 1 (MALAT1) to recipient HUVECs and stimulate angiogenesis-related gene expression in recipient human umbilical vein endothelial cells (HUVECs), eventually promoting angiogenesis." (PMID 37497408, 2023). "MALAT1, often upregulated in other cancers is also found to be overexpressed in ovarian cancer cells." (PMID 39912983, 2025). "MALAT-1 expression was found to be significantly upregulated in ovarian cancer tissues compared to normal tissues." (PMID 40861865, 2025). "MALAT1: Known to promote epithelial-mesenchymal transition (EMT) in ovarian cancer, circulating MALAT1 serves as a marker of aggressive disease and poor prognosis." (PMID 39912983, 2025). "Targeting MALAT1 through siRNA knockdown significantly diminishes ovarian cancer cell viability, impedes migration, and reduces invasion capabilities." (PMID 39323624, 2024). "While the full implication of the lncRNAs MIAT rs1061540 and MALAT1 rs3200401 in ovarian cancer development remains to be determined, it is clear that MIAT rs1061540 played a role in modulating the risk of this disease in the present study cohort." (PMID 38390896, 2024). "Supported by a late report, MALAT1 targets miR-503-5p, thus to induce proliferation and suppress apoptosis of ovarian cancer cells." (PMID 35046387, 2022). "Silencing of MALAT1 accelerated cisplatin sensitivity in ovarian cancer by suppression of the Notch1 pathway and ABCC1 expression." (PMID 36105363, 2022). "Knockdown of MALAT1 upregulated Bax protein and downregulated Bcl-2 protein in ovarian cancer cells." (PMID 36105363, 2022). "Knockdown of MALAT1 in ovarian cancer cells changes the expression of many genes related to cell proliferation, metastasis, and apoptosis, and inhibition of MALAT1 can significantly inhibit the tumorigenicity of SKOV3 cells." (PMID 35103065, 2022). "Pro-angiogenic genes VEGF-A, VEGF-D, IL-8, and angiogenin were found to be stimulated by lncRNA MALAT1 derived from epithelial ovarian cancer cell exosomes." (PMID 34067896, 2021). "LncRNA-plasmacytoma variant translocation I (PVT1), metastasis-associated lung adenocarcinoma transcript 1 (MALAT1), and LINC00319 were demonstrated to be involved in ovarian cancer cell proliferation, migration, and invasion by acting as a ceRNA." (PMID 34900667, 2021). "Another evidence of MALAT-1’s contribution to ovarian cancer progression is provided by Zhou and his team." (PMID 34207450, 2021). "Metastasis associated lung adenocarcinoma transcript 1 (MALAT1) is upregulated in several cancers, including lung, bladder, breast, prostate and ovarian cancers, and serves as a potential biomarker and therapeutic target." (PMID 34124072, 2021). "MALAT1 contributes to the aggressive behavior and worst prognosis of ovarian cancer by sequestering diverse microRNAs." (PMID 34204094, 2021). "Serum analyses for biomarkers have revealed upregulation of MALAT1 in epithelial ovarian cancer, UEGC1 and HotTip (gastric cancer), and HOTAIR (glioblastoma multiforme)." (PMID 34067896, 2021). "Then, MALAT1 suppression inhibited ovarian cancer cell migration and invasion and regulated the MAPK pathway via a variety of mechanisms, including reducing MERK1, ERK1, P38 and JNK phosphorylation." (PMID 34288373, 2021). "Previous studies demonstrated that MALAT1 promotes proliferation and suppresses apoptosis in ovarian cancer by sponging miRNAs such as miR-211." (PMID 34681900, 2021). "For instance, a recent study disclosed that MALAT1 was strikingly elevated in ovarian cancer, and its depletion retarded cell growth and metastasis in vitro." (PMID 34222668, 2021). "As above reported, MALAT1, a lncRNA, previously related to ovarian cancer, and to epithelial to mesenchymal transition (EMT), was detected in our results of EOC-HMGB1-interactome." (PMID 32867128, 2020).
ovarian carcinoma (continued). "The PIK3/Akt pathway has been shown to play a critical role in MALAT1 induced metastasis and cisplatin resistance in gastric, cervical, and ovarian cancers." (PMID 32708561, 2020). "33, 34 Furthermore, MALAT1 regulated ovarian cancer cell proliferation, migration and apoptosis through Wnt/β‐catenin signalling pathway." (PMID 31250518, 2019). "For example, lncRNA MALAT1 promoted proliferation and metastasis of epithelial ovarian cancer via the PI3K-AKT pathway; lncRNA SNHG14 enhanced proliferation and metastasis of ovarian cancer by sponging miR-219a-5p." (PMID 31794425, 2019). "Recent study has focused on the role of an exosomal long non-coding RNA in angiogenesis and showed that the long non-coding RNA, metastasis-associated lung adenocarcinoma transcript 1 (MALAT1), in ovarian cancer-derived exosomes can be transferred to HUVECs." (PMID 31405096, 2019). "A qualitative evaluation of ovarian cancer revealed the top 20 predictions by LION contained all four experimentally validated lncRNAs: MALAT1, H19, HOTAIR, and PVT1." (PMID 31379598, 2019). "In the microarray analysis of lncRNAs, MALAT1 was found to be significantly increased in ovarian cancer tissues and different ovarian cancer cell lines." (PMID 29921308, 2018). "Lately, six lncRNAs RUNX1-IT1, MALAT1, H19, HOTAIRM1, LOC100190986 and AL132709.8 were validated to be associated with recurrence of ovarian cancer through using the microarray data preprocessing." (PMID 29921308, 2018). "The long non-coding RNA MALAT1 was identified as a highly promiscuous fusion transcript in ovarian carcinoma." (PMID 30416686, 2018). "In the DisLncPri predicting result list, we found 4 novel lncRNAs in top 20 (GAS5 at 1, MALAT1 at 4, MEG3 at 6 and HOTAIR at 9) that were recently associated with ovarian cancer." (PMID 27992375, 2017). "A recent study found that MALAT1 was deregulated in ovarian cancer and postulated to play a suppressive role." (PMID 27992375, 2017). "MALAT1 is also overexpressed in the ovarian cancer cell line SKOV3ip, which is derived from SKOV3 with a more metastatic phenotype." (PMID 28637507, 2017). "MALAT-1 mRNA expression in control normal ovary and primary ovarian cancer tissues was evaluated by qRT-PCR and normalized to an internal control (β-actin)." (PMID 27227769, 2016). "Further exploration of the target genes and signaling pathway will provide new insight into the molecular mechanisms of MALAT-1 involved in ovarian cancer progression and will aid in construction of a stronger prediction and prevention rule in ovarian cancer." (PMID 27227769, 2016). "Expressions of MALAT-1 were detected in 37 normal ovarian tissues and 45 ovarian cancer tissues by reverse transcription polymerase chain reaction (RT-PCR)." (PMID 27227769, 2016). "To further elucidate the molecular mechanisms of MALAT-1-induced metastasis, we identified genes regulated by MALAT-1 expression, by comparing shRNA-inhibited versus control ovarian cancer cells." (PMID 27227769, 2016). "Expression of MALAT-1 in ovarian cancer tissues is significantly higher than that of in normal ovary." (PMID 27227769, 2016). "In the current study, we examined MALAT-1 expression in epithelial ovarian cancer tissues and investigated the role of MALAT-1 in the regulation of tumor cell migration and invasion in vitro." (PMID 27227769, 2016). "Because knockdown of MALAT-1 inhibited cell proliferation,we then examined MALAT-1 function in regulating ovarian cancer cell cycle progression and apoptosis." (PMID 27227769, 2016). "Additionally, Malat1 has also been shown to promote ovarian cancer through the regulation of splicing factor RBFOX2." (PMID 40861865, 2025). "Additionally, it has been discovered that MALAT-1-mediated control of EMT in ovarian cancer cells involves the PI3K/AKT signaling pathway." (PMID 38511067, 2024).